TNF (tumor necrosis factor)
Diseases named in the same sentence as TNF in open-access papers (continued):
Sharing a sentence is not in itself a finding about the gene and the disease.
sickle cell disease (25 papers, 2009 to 2025). Sickle cell anemias are chronic hemolytic diseases that may induce three types of acute accidents: severe anemia, severe bacterial infections, and ischemic vasoocclusive accidents (VOA) caused by sickle-shaped red blood cells obstructing small blood vessels and capillaries. "The findings of this study specifically implicate TNFα and mononuclear cell binding to endothelium as key mediators, and that circulating mononuclear cells in sickle cell disease are predisposed to induce cathepsin proteolytic activity." (PMID 22550569, 2012). "Oral zinc acetate protects patients with sickle cell disease from upper respiratory tract infection, reducing the proinflammatory cytokines TNF‐α and IL‐1β secreted by Th1 cells." (PMID 38801402, 2024). "Sickle cell disease patients showed significantly higher markers of endothelial function (TNF-α, IL-6, and IL-17A) in comparison to controls (p-values < 0.001, < 0.001, and 0.006, respectively)." (PMID 39354381, 2024). "We found that apart from being a nociceptive agent, flurbiprofen exerts a strong anti-inflammatory effect by suppressing NF-κB signaling, which was evidenced by reduced levels of TNF-α and IL-6 in wild-type and sickle cell disease Berkeley mice models." (PMID 37180702, 2023). "A human study demonstrated that patients with sickle cell disease had higher levels of TNF-α and blood viscosity when compared to healthy individuals." (PMID 37627021, 2023). "Monocytes are thought to be activated in sickle cell anaemia by the expression of TNF-alpha and IL-1 beta as well as the adhesion of molecule ligand (CD11b)." (PMID 33827455, 2021). "Plasma concentrations of the pro-inflammatory cytokines TNF-α and IL-1β, the adhesion molecule sICAM-1 and the anti-inflammatory cytokine IL-10 were measured in a total of 55 adult subjects with sickle cell disease and 17 haemoglobin AA controls." (PMID 23922670, 2013). "TNF-α and whole blood viscosity at 46 sec-1 and 230 sec-1 (1.75, 2.02 vs. 0.83, 1.26, p<0.05) were significantly greater in sickle cell disease subjects than in controls." (PMID 23922670, 2013). "Median TNF-α (p = 0.001) concentration was significantly increased in the sickle cell disease group." (PMID 23922670, 2013). "Sickle cell disease patients with more severe genotypes (SS and Sβ0) had slightly greater levels of markers of endothelial function (TNF-α, IL-6, and IL-17A) than Sβ+ patients, but the difference was not statistically significant (p-values = 0.173, 0.583, and 0.720, respectively)." (PMID 39354381, 2024). "Moreover, monocytes are activated in sickle cell disease with expression of tumour necrosis factor alpha (TNF-α) and interleukin-1 beta (IL-1β) as well as adhesion of molecule ligand, CD11b." (PMID 33238928, 2020). "It was also demonstrated that zinc as an antioxidant could reduce the levels of oxidative stress biomarkers and inflammatory cytokines such as TNF-α and IL-1β in patients with sickle cell disease." (PMID 30127816, 2018). "Likewise, increased exposure to inflammatory cytokines such as interleukin-6 and tumor necrosis factor-α and angiogenic factors such as PDGF and VEGF has been associated with altered cardiac function in settings other than sickle cell disease." (PMID 19956689, 2009). "Levels of pro-inflammatory cytokines, such as tumor necrosis factor (TNF), interleukin-1 (IL-1), interleukin-8 (IL-8), and prostaglandin E2 (PGE2), are commonly increased in sickle cell disease." (PMID 39846606, 2025). "Compared to a group of healthy controls, sickle cell disease patients had lower plasma zinc, increases in markers of oxidative stress, elevated VCAM-1, increased production of TNF-α and IL-1β, and decreased IFN-γ production at baseline." (PMID 34239993, 2021). "It is well-known that hydroxycarbamide (hydroxyurea), a cytoredutor drug indicated for MPN treatment, is capable of lowering serum inflammatory markers such as TNF-α, IL-6, CXCL8, and IL-1β in sickle cell disease patients." (PMID 34084749, 2021).
sickle cell disease (continued). "The immunological aspects of SCD have been widely studied among individuals with sickle cell anemia (SCA), with high levels of cytokines detected, including interleukin (IL) 4, 6, 8, 10, and tumor necrosis factor-alpha (TNF-a)." (PMID 33149723, 2020). "The involvement of the pro-inflammatory cytokines IL-1β and TNF-α in promoting endothelial adhesiveness, leukocyte activation and the coagulation cascade could render them potent mediators of episodic vasoocclusion in sickle cell disease and in promoting chronic leg ulcers." (PMID 23922670, 2013). "Regarding sickle cell disease, previous evaluation of monocytes subsets has identified that non-classical or patrolling monocytes express low levels of TNF-α and IL-6 and they seem to be important protecting the microvasculature from VOE35." (PMID 31616024, 2019). "Furthermore, consistent with previous reports suggesting an up-regulation of inflammatory pathways in sickle cell disease vs. controls, we found significantly greater concentrations of the inflammatory cytokine TNF-α, but not IL-1β or the adhesion molecule, ICAM-1 in the sickle cell disease group." (PMID 23922670, 2013).
thyroid (25 papers, 2009 to 2026). "In thyroiditis, infiltrating pro-inflammatory cytokines (e.g., TNF-α and IFN-γ) induce inflammasome activation and thyrocyte apoptosis." (PMID 40831950, 2025). "IL-10 mitigates inflammation in early thyroiditis by inhibiting Th1 cytokines like TNF-α and IL-1, while in later stages, Th2 cell activation promotes humoral responses." (PMID 39104791, 2024). "These authors did not report what influence drug treatment had on their sample, but others have noted that the frequency of thyroid disorder was lower in SpA patients receiving anti-TNF-alpha treatment." (PMID 29267515, 2017). "Due to its multiple immunological mechanisms, TNF-α has been previously investigated in thyroid patients." (PMID 28824542, 2017). "ROC curves also validated that TNF-α was a potential marker for distinguishing patients with thyroid diseases from the healthy subjects." (PMID 26881177, 2016). "Therefore, IL-6, IL-15, and TNF-α were selected as representative indicators in this study to explore the potential interplay among thyroid function, inflammatory state, and skeletal muscle metabolism." (PMID 41355999, 2025). "Different models of thyroid damage applied in the experiment resulted in no significantly different effects on the TNF-α, IL-6, and IL-10 levels." (PMID 30927245, 2020). "The main possible mechanisms underlying this phenomenon are as follows: (a) IL-2 and IFN-γ may participate in the thyroid autoimmune process and affect thyroid function by blocking the PD-1/PD-L1 pathway; (b) IFN-γ and TNF-α produced by Th1 cells induce the release of CXCL10 from thyroid cells." (PMID 37051293, 2023).
age-related macular degeneration (24 papers, 2010 to 2026). Age-related loss of vision in the central portion of the retina (macula), secondary to retinal degeneration. "In this study, we aimed to determine the association between TNF-863A/C (rs1800630), TNF-308A/G (rs1800629), and TNF-238A/G (rs361525) single-nucleotide polymorphisms, TNF-α serum levels and the pathogenesis of age-related macular degeneration." (PMID 35888018, 2022). "One study was found in the scientific literature that investigated TNF-863 A/C (rs1800630) SNP with age-related macular degeneration (AMD)." (PMID 38999258, 2024). "In fact, TNF-α modulation has recently started to be considered in the context of refractory diabetic macular edema or choroidal neovascularization secondary to age-related macular degeneration." (PMID 21152396, 2010). "The potential toxicity of TNF-α antibodies to the retina first received attention two decades ago, triggered by the introduction of the intravitreal route of administration to target wet macular degeneration." (PMID 37803488, 2024). "PEDF can improve retinal diseases, such as age-related macular degeneration, by effectively downregulating the mRNA expression of pro-inflammatory cytokines, such as tumor necrosis factor alpha (TNF-α), interleukin (IL)-1β, inducible nitric oxide synthase (iNOS), and IL-17a." (PMID 38164244, 2023). "Both DR and age-related macular degeneration are chronic inflammatory diseases that involves the activation of the microglia, monocytes-macrophages, neutrophils, and lymphocytes as well as the secretion of inflammatory mediators, including IL-6, TNF-α, MCP-1, and VEGF." (PMID 36712506, 2022). "As far as we know, the regulation of the expression of TNFα by light has not been previously reported; nevertheless, this could be in agreement with the inflammatory mechanism that underlines the age-related macular degeneration induced or exacerbated by blue light." (PMID 34831470, 2021). "TNF-α, by means of complement activation and induction of reactive oxygen species, plays a major role in the pathogenesis of age-related macular degeneration (AMD)." (PMID 32151118, 2020). "Moreover, combination therapy with TNF-α and VEGF inhibitors was shown to improve clinical outcomes in patients with age-related macular degeneration (AMD) and macular edema." (PMID 37631272, 2023). "Due to this reason, our study aimed to determine the associations of tumor necrosis factor-alpha (TNF-α) gene single-nucleotide polymorphisms (SNPs) TNF-863A/C (rs1800630), TNF-308A/G (rs1800629), TNF-238A/G (rs361525), and TNF-α serum concentration with age-related macular degeneration." (PMID 35888018, 2022). "In our previous study on age-related macular degeneration, a miRNA array revealed that miR-1285 was downregulated in ARPE-19 cells treated with the inflammatory cytokine TNF-α; TNF-α is one of the most prominent inflammatory cytokines, and its mRNA and proteins are widely expressed in PVR membranes." (PMID 34383767, 2021).
autism spectrum disorder (24 papers, 2013 to 2025). A spectrum of developmental disorders that includes autism, and Asperger syndrome. "It has been suggested that the underlying mechanism of autism spectrum disorders might be brain inflammation associated with increased inflammatory cytokines such as IL-6 and TNF-α." (PMID 38905296, 2024). "Autism spectrum disorders (ASDs) have been associated with brain inflammation as indicated by microglia activation, as well as brain expression and increased plasma levels of interleukin-6 (IL-6) and tumor necrosis factor (TNF)." (PMID 26418275, 2015). "Studies suggest that RES may alleviate the core and associated symptoms of the autism spectrum disorders rat phenotype by reducing oxidative stress, decreasing the expression of tumor necrosis factor-α (TNF-α) and MMP-9, and addressing mitochondrial dysfunction." (PMID 38933889, 2024). "Levels of TNF-α, an inflammatory biomarker found in the brain and CSF of many autistic people, have been found to be positively correlated with the severity of autism spectrum disorders." (PMID 38148790, 2023). "One clinical trial found reductions in the production of IL-13 and a decrease in the frequency of CD8+ T cells expressing TNF-α in the group of children with autism spectrum disorder (ASD) after they received treatment with BC products." (PMID 37834178, 2023). "Samples from the brain and cerebrospinal fluid of patients with autism spectrum disorders show increased contents of inflammatory molecules, such as IL-1β, IL-6, TNF-α, MCP-1, and CXCL8/IL-8." (PMID 33506033, 2021). "Also, it has been demonstrated that vinpocetine suppressed elevated brain levels of IL-6 and TNF-α, and augmented brain level of IL-10, in a rat model of autism spectrum disorder." (PMID 36594060, 2023). "In the Valproic acid-induced autism spectrum disorder model of rats, oral administration of 20, 40, and 80 mg/kg of BM methanolic extract for 20 days decreased the inflammation in the hippocampus and prefrontal cortex by decreasing the IL-1β, IL-6, and TNF-α levels dose-dependently." (PMID 40297338, 2025). "In the propionic acid-induced rat model of autism spectrum disorder (ASD), oral administration of 250 mg/kg and 500 mg/kg hydroalcoholic extract of BM for 28 days is found to dose-dependently reduce the TNF-α in brain tissues along with cognitive improvements." (PMID 40297338, 2025). "In another meta-analysis patients with an autism spectrum disorder were reported to have increased blood concentrations of IL-1β, IL-6, IFN-ɣ and TNF-α." (PMID 34589729, 2021).
colorectal adenoma (24 papers, 2010 to 2025). An adenoma that arises from the colon or rectum. "Elevated serum levels of TNF-α show a marked relationship with the increased risk of colorectal adenomas in men28, and suppressing TNF-α signaling reduced the number and size of polyps in an animal model." (PMID 37729351, 2023). "For highest vs. lowest levels, results from this meta-analysis did not support an association between circulating levels of CRP [OR (95% CI): 1.15 (0.94-1.40)], IL-6 [1.17 (0.94-1.46)] and TNF-α [0.99 (0.75-1.31)] and risk of colorectal adenomas, respectively." (PMID 27608842, 2016). "In a recent study analyzing the association between plasma cytokines and the presence of colorectal adenoma, TNF-α was higher in individuals with colorectal adenomas than in controls." (PMID 24465801, 2014). "In this study, we found a borderline association between plasma TNF-α levels and colorectal adenomas." (PMID 23442743, 2013). "Previous studies regarding associations between IL-6 and TNF-α levels and colorectal adenomas are inconsistent." (PMID 24235998, 2013). "It has been reported that the transcription of the metalloproteinase gene is positively regulated by cytokines and growth factors such as interleukins (IL1β) or TNFα suspected to be associated with the formation of colorectal adenoma in humans." (PMID 22735354, 2012). "Previous research from our group has shown that increased levels of circulating, pro-inflammatory cytokines IL-6 and TNFα promote colorectal adenoma risk." (PMID 20500855, 2010). "Prior studies from our group demonstrated that increased systemic levels of pro-inflammatory cytokines IL-6 and TNFα correlate with risk of colorectal adenoma." (PMID 20500855, 2010). "Consistent with our findings, one study of colorectal adenoma reported that the use of NSAIDs was positively associated with high levels of other inflammatory proteins, IL‐6 and TNF‐alpha, which the authors concluded could be due to confounding by indication." (PMID 39482824, 2025). "Additionally, it was suggested that increased concentrations of chemerin and TNF-α were associated with an increased risk of colorectal adenoma, and the associated inflammation was important in the early stage of CRC development." (PMID 36005576, 2022). "This chronic inflammatory condition or secretory molecules such as reactive oxygen species, interleukin (IL)-6, and tumor necrosis factor (TNF)-α could be associated with the occurrence of colorectal adenoma." (PMID 36548355, 2022). "A recent case-control study involving African Americans showed an increased risk of colorectal adenoma onset associated with high circulating levels of TNF-α, IGF-1, and the metabolic biomarker adiponectin, which is secreted from the abdominal fat tissue and can induce cell proliferation." (PMID 32258104, 2020). "The aims of this study were to examine whether serum concentrations of IL-1β, IL-2, IL-8, IL-10, IL-12p70, GMCSF, IFNγ, and TNFα were associated with flavonol intake or could predict colorectal adenoma recurrence." (PMID 20924374, 2010). "Previously published results on colorectal adenomas found that a high abundance of F. nucleatum was positively correlated with the expression of inflammatory cytokine genes, such as IL-6 and TNF-α, which is similar to our findings." (PMID 38075864, 2023). "In a study about colorectal adenomas, the abundance of F. nucleatum was found to positively correlate with inflammatory cytokine genes expression including that of TNF, which was consistent with our result." (PMID 27323816, 2016). "Several studies on colorectal adenomas have also demonstrated a positive correlation between elevated Fusobacterium nucleatum levels and increased expression of inflammatory cytokines, including IL-6 and TNF-α." (PMID 41267807, 2025). "In addition, McCoy and coauthors observed a significant positive link between IL-10 and TNF-α gene expression and Fn in colorectal adenomas, suggesting their potential role in gut mucosal inflammation." (PMID 32258104, 2020).
colorectal adenoma (continued). "Recent evidence indicates that TNF-α serum level may be elevated in patients with colorectal adenoma that is consistent with our results." (PMID 29593647, 2018). "In conclusion, we demonstrated that circulating levels of adiponectin, TNF-α, and IGF-1 were associated with colorectal adenoma risk and as such might be good biomarkers for colorectal adenoma risk in African Americans." (PMID 29593647, 2018). "In addition, in a study about colorectal adenomas, the abundance of F. nucleatum was found to positively correlate with inflammatory cytokine gene expression such as TNF." (PMID 29375539, 2017). "The departure from a linear relationship was not significant between CRP (Pfor nonlinearity=0.18), IL-6 (Pfor nonlinearity=0.35) and TNF-α (Pfor nonlinearity=0.87) and risk of colorectal adenoma, respectively." (PMID 27608842, 2016). "Recent evidence indicates that serum levels of IL-6 and TNF-α may be elevated in those with colorectal adenoma." (PMID 24235998, 2013). "The F. varium-stimulated DC line produced high levels of IL-6, IL-8, or TNF-α, consistent with our previous report indicating that F. varium in actively inflamed colonic mucosa was associated with the progression of UC36 and the pathogenesis of colorectal adenoma and intramucosal CRC25." (PMID 35739324, 2022). "IL-6 and TNF-α have been associated with colorectal adenoma in a few studies but not in others." (PMID 24235998, 2013). "In the current study, we examined serum concentrations of eight cytokines (IL-1β, IL-2, IL-8, IL-10, IL-12p70, GMCSF, IFNγ, and TNFα) in relation to flavonol intake and colorectal adenoma recurrence and found none to be associated with flavonol intake and with colorectal adenoma recurrence." (PMID 20924374, 2010). "The potential role of adiponectin, leptin, IGF-1, and tumor necrosis factor alpha (TNF-α) as biomarkers in colorectal adenoma is not clear." (PMID 29593647, 2018). "Results from publications on inflammatory markers of C-reactive protein (CRP), interleukin-6 (IL-6) and tumor necrosis factor-α (TNF-α) and risk of colorectal adenomas are not consistent." (PMID 27608842, 2016). "Similarly, the AUC with 95% confidence intervals to assess the sensitivity and specificity of the biomarkers for colorectal adenoma diagnosis corresponded to 0.75 (0.70–0.80), 0.71 (0.66–0.77), and 0.64 (0.59–0.70) for adiponectin, IGF-1, and TNF-α, respectively." (PMID 29593647, 2018). "In summary, circulating levels of CRP, IL-6 and TNF-α may be not useful biomarkers for identifying colorectal adenomas." (PMID 27608842, 2016). "No nested case-control study on circulating levels of TNF-α and colorectal adenomas was identified." (PMID 27608842, 2016). "Circulation levels of CRP, IL-6 and TNF-α might be not useful biomarkers for identifying colorectal adenomas, respectively." (PMID 27608842, 2016). "However, a meta-analysis of study results showed that TNF-α could not be a useful biomarker for the identification of colorectal adenomas." (PMID 36005576, 2022).